SOX9 (SRY-box transcription factor 9)
Diseases named in the same sentence as SOX9 in open-access papers (continued):
Sharing a sentence is not in itself a finding about the gene and the disease.
head and neck squamous cell carcinoma (4 papers, 2016 to 2024). A squamous cell carcinoma that arises from any of the following anatomic sites: lip and oral cavity, nasal cavity, paranasal sinuses, pharynx, larynx, and salivary glands. "MiR-145 targets the SOX9/ADAM17 axis in the head and neck squamous cell carcinoma." (PMID 26657507, 2016). "In PCa and head and neck squamous cell carcinoma (HNSCC) models, NR2F1 induced a dormant phenotype by regulating the H3K4me3 and H3K27me3 epigenetic marks in the promoter of SOX9 and RARβ." (PMID 34208521, 2021). "The orphan nuclear receptor (NR2F1) regulates tumor cell dormancy in head and neck squamous cell carcinoma (HNSCC) by coordinating the hypermethylation of H3 histone proteins (H3K27, H3K9, and H3K4), bounded to SOX9, RARβ, and CDK inhibitors to inhibit cell proliferation." (PMID 38994941, 2024).
Insulin resistance (4 papers, 2016 to 2025). Increased resistance towards insulin, that is, diminished effectiveness of insulin in reducing blood glucose levels. "Functional enrichment analysis showed that SOCS3, IL6, FOXO1, CEBPB, SOX9, and PPARGC1A were mainly involved in the adipocytokine signaling pathway, insulin resistance, FoxO signaling pathway, AMPK signaling pathway, and PI3K-Akt signaling pathway." (PMID 38415055, 2024). "Nevertheless, whether SOX9 and GSK3β have reciprocal regulatory relationship, how these regulations occur, and how they participate in insulin resistance are still not clear." (PMID 35281088, 2022).
invasive breast carcinoma (4 papers, 2014 to 2020). A carcinoma that infiltrates the breast parenchyma. "Considering the potential influence of SOX9 in LAM pathogenesis, cytoplasmic positivity has been associated with invasive breast cancer and metastasis, but normal differentiated mammary epithelia generally exhibit nuclear localization." (PMID 26167915, 2015). "Physiological significance is supported by the recapitulation of EMT and Sox9 signatures recorded with model tumor lines by primary invasive breast cancers." (PMID 25291178, 2014).
ischemia (4 papers, 2020 to 2022). A hypoperfusion of the BLOOD through an organ or tissue caused by a PATHOLOGIC CONSTRICTION or obstruction of its BLOOD VESSELS, or an absence of BLOOD CIRCULATION. "More importantly, a previously conducted study has suggested that upregulation of SOX9 has the potential to worsen hepatic ischemia/reperfusion injury via promoting inflammation and apoptosis." (PMID 33791290, 2020). "Another study reported that the elevation of SOX9 could activate TGF-β1 to exacerbate hepatic ischemia/reperfusion (IR) injury." (PMID 35586685, 2022). "In pulmonary branching morphogenesis, β-catenin inhibits the expression of SOX9 in basal cells critically, and SOX9 could enhance hepatic ischemia/reperfusion injury by promoting TGF-β1 expression." (PMID 34531378, 2021).
leukemia (4 papers, 2015 to 2025). A malignant (clonal) hematologic disorder, involving hematopoietic stem cells and characterized by the presence of primitive or atypical myeloid or lymphoid cells in the bone marrow and the blood. "The NF-YA ChIP-seq data from ENCODE (Accession number: ENCSR000EGR; k562, human leukemia cells) contained 7647 peaks, of which 2564 overlapped with our SOX9 ChIP-seq peaks." (PMID 26040697, 2015). "Modulation of the SOX9 gene was shown here to affect adipogenic potential and resultant support of leukemia progenitor cells." (PMID 31492897, 2020).
Micrognathia (4 papers, 2014 to 2025). Developmental hypoplasia of the mandible. "For example, micrognathia is often seen as part of the Pierre Robin sequence that is mostly caused by mutations in SOX9." (PMID 40136761, 2025). "Thus, the SOX9 protein has been found to be involved in the formation of craniofacial structures, and patients with gene variants present with micrognathia, cleft lip and palate, and craniofacial malformations." (PMID 35805171, 2022). "However, the heightened sensitivity of the mandible to SOX9 gene dosage further restricts the manifestations to micrognathia, which can, in sequence, lead to additional PRS-associated phenotypes." (PMID 32991838, 2020). "Some affected individuals within the SOX9 CRM families had micrognathia as their sole phenotype." (PMID 24363063, 2014).
neuroblastoma (4 papers, 2014 to 2022). Neuroblastoma (NB) is the most common solid, extracranial childhood tumor. "The expression of Sox9 in Neuro2a cells (murine neuroblastoma) causes concomitant induction of several glial markers." (PMID 24711445, 2014). "Similar interaction has been identified in neuroblastoma in which significantly decreased SPOCK1 RNA levels were detected in SOX9 knockout neuroblastoma cells." (PMID 35221802, 2022). "Despite the up regulation of some other EMT inducers such as SOX9 and EOMES upon TRPM7 knockdown, these results suggest that TRPM7 maintains epithelial-like neuroblastoma cells in a progenitor-like migratory state." (PMID 25797249, 2015).
Obesity (4 papers, 2022 to 2025). Accumulation of substantial excess body fat. "Similarly, the SOX9 mRNA expression level was highest in patients with class II + III obesity; however, it lowest in patients with class I obesity." (PMID 40004707, 2025). "The lowest SOX5 and SOX9 mRNA expression levels in OA-affected synovium were noted in overweight patients, and the highest in patients with class II + III obesity." (PMID 40004707, 2025). "The cause of decreased collagen II in knee cartilage of the 7-day male mouse offspring in the maternal obesity group was investigated by examining the collagen II-related transcription factors RUNX2 and SOX9 at the mRNA and protein levels." (PMID 35327669, 2022). "Our study revealed only SOX5 mRNA expression level in OA-affected articular cartilage with subchondral bone was positively correlated with BMI; however, we noticed SOX9 and SOX11 mRNA expression level was higher in patients with class II + III obesity compared to patients with class I obesity." (PMID 40004707, 2025). "Moreover, we observed decreased AMPK activity and SOX9 levels in mouse chondrocytes upon FFA exposure but increased levels after TMZ treatment, which was consistently observed in HFD mouse models and human OA samples from individuals with obesity." (PMID 40425566, 2025).
osteoporosis (4 papers, 2021 to 2025). A condition of reduced bone mass, with decreased cortical thickness and a decrease in the number and size of the trabeculae of cancellous bone (but normal chemical composition), resulting in increased fracture incidence. "In osteoporosis, VSMC can be transformed into osteoblast-like cells, with the induction of markers such as runt-related transcription factor 2 (Runx2), SRY-Box 9 (Sox9), etc.." (PMID 35498045, 2022).
prostate (4 papers, 2012 to 2022). "The transcription factor SOX9 plays a crucial role in normal prostate development and has been suggested to drive prostate carcinogenesis in concert with PTEN inactivation." (PMID 26030748, 2015). "Deletion of Sox9 in two GEMMs of prostate tumorigenesis prevents cancer development indicating an essential role for Sox9 in PCa." (PMID 25277175, 2014). "This block in carcinogenesis suggests the possibility that Sox9 maintains a prostate epithelial lineage that is responsive to additional oncogenic stimuli and thereby allows for the initiation of prostate carcinogenesis." (PMID 22761195, 2012). "Given the role of Sox9 in the initiation of prostate organogenesis, we sought to determine its role in the initiation of prostate carcinogenesis." (PMID 22761195, 2012).
renal cell carcinoma (4 papers, 2019 to 2024). "Circular RNA EHD2 (CircEHD2) from renal cell carcinoma cell-derived EVs activates CAFs to accelerate the growth of renal cell carcinoma cells via the circEHD2/YWHAH/YAP/SOX9 signaling pathway." (PMID 39759028, 2024). "MiRNA-138-induced SOX9 suppression prevents renal cell carcinoma progression." (PMID 38132479, 2023). "SOX9 contributes to cell proliferation and invasion in renal cell carcinoma." (PMID 38132479, 2023). "CircEHD2 and YAP bind to the SOX9 promoter and activate the expression SOX9 with the help of YWHAH, and consequently facilitate the proliferation and migration of renal cell carcinoma." (PMID 39550559, 2024).
skin tumors (4 papers, 2013 to 2024). "The precise relationship and functional roles of Sox9 in establishing skin cancers, however, should be investigated further." (PMID 23349860, 2013). "SOX2 and SOX9 regulate skin tumors, including squamous cell carcinoma." (PMID 39684417, 2024).
squamous cell carcinoma (4 papers, 2013 to 2024). A carcinoma arising from squamous epithelial cells. "For their part, SOX2 and SOX9 are stem factors that play an important role in the acquired resistance of squamous cell carcinoma (SCC) to cisplatin: the detailed mechanism of this feature is the switch from SOX2+ to SOX9+ mediated by SE remodeling." (PMID 34011395, 2021). "Nuclear staining of Sox9 was also detected in a low-grade skin tumor keratoacanthoma (KA), and squamous cell carcinoma (SCC)." (PMID 23349860, 2013). "SOX9 could enhance squamous cell carcinoma cells’ colony-forming activity." (PMID 36003340, 2022).
urothelial carcinoma (4 papers, 2013 to 2026). A malignant neoplasm derived from the transitional epithelium of the urinary tract (urinary bladder, ureter, urethra, or renal pelvis). "Urothelial carcinoma cells are greatly affected by the expression of stem-cell-associated factors and transcription factors involved in early developmental differentiation, such as SOX9, which promote their differentiation and invasion." (PMID 38002064, 2023). "In this study, miR-138 and its candidate target molecule, SOX9, were found to be involved in the proliferation of urothelial carcinoma cell lines." (PMID 38002064, 2023). "Immunohistochemical staining was performed to evaluate the expression of SOX9 protein in the carcinoma lesions of 67 urothelial carcinoma cases (pTa: 25 cases, pT1: 17 cases, pT2: 12 cases, and pTis: 13 cases) collected during TUR." (PMID 38002064, 2023). "miR-138 precursor transfection of T24 and UMUC2 cells significantly decreased SOX9 expression, indicating that SOX9 is a miR-138 target in urothelial carcinoma." (PMID 38002064, 2023). "Expression of SOX9 was significantly higher in invasive urothelial carcinoma cells than in non-invasive urothelial carcinoma cells, suggesting that miR-138 and SOX9 affect the invasive potential of these cells." (PMID 38002064, 2023). "The expression levels of SOX9 mRNA and miR-138 in urothelial carcinoma tissues were examined via quantitative RT-PCR analysis using RNA extracted from FFPE tissue samples." (PMID 38002064, 2023). "In conclusion, we found that miR-138 regulated the growth and invasive potential of urothelial carcinoma cells by suppressing the expression of SOX9." (PMID 38002064, 2023). "In contrast, SOX9 expression was very low in low-grade non-invasive urothelial carcinomas with preexisting urothelial cell characteristics." (PMID 38002064, 2023). "Here, we demonstrated that SOX9 plays an important role in the invasion of tumor cells at the cellular level, explaining the high expression of SOX9 in invasive urothelial carcinoma cells." (PMID 38002064, 2023). "SOX9 protein levels are elevated in invasive human uroepithelial carcinoma tissues, which are induced by the activation of epidermal growth factor receptor." (PMID 23687991, 2013). "Matrigel assays revealed that miR-138 overexpression suppressed the invasion of urothelial carcinoma cells, similar to the suppression of SOX9 expression, suggesting that increased miR-138 expression and decreased SOX9 expression are critical for the growth and invasion of urothelial carcinoma." (PMID 38002064, 2023). "Notably, induction of miR-138 expression and suppression of SOX9 expression can suppress the invasive potential of urothelial carcinoma cells." (PMID 38002064, 2023). "In this study, we analyzed the functions of miR-138 and SOX9 in urothelial carcinoma." (PMID 38002064, 2023). "Moreover, miR-138 precursor or SOX9 small interfering RNA (siRNA) transfection decreased the proliferation of urothelial carcinoma cell lines." (PMID 38002064, 2023). "Using these two cell types, we decided to analyze the function of SOX9 in urothelial carcinoma." (PMID 38002064, 2023). "Interestingly, ERK1/2 and SOX9 signaling pathways were recently shown to interact in urothelial carcinoma and zebrafish sex determination." (PMID 29038159, 2017). "In urothelial carcinoma, the activation of EGFR can upregulate the expression of SOX9 via the ERK signaling pathway, thereby promoting tumor occurrence; the EGFR-ERK-SOX9 signaling cascade mechanism suggests that a similar regulatory pathway may also exist in EGFR-mutated NSCLC." (PMID 41268614, 2026).
achondroplasia (3 papers, 2008 to 2026). Achondroplasia is the most common form of chondrodysplasia, characterized by rhizomelia, exaggerated lumbar lordosis, brachydactyly, and macrocephaly with frontal bossing and midface hypoplasia. "The gain-of-function mutant of Fgfr3 causes achondroplasia, Sox9 controls chondrocyte differentiation via Sox5 and Sox6 expression, and Ihh is a master gene of bone development under BMP control, suggesting that Slc39a13 exerts a profound influence on genes crucial to chondrocyte differentiation." (PMID 18985159, 2008).
Alzheimer disease (3 papers, 2022 to 2023). A progressive, neurodegenerative disease characterized by loss of function and death of nerve cells in several areas of the brain leading to loss of cognitive function such as memory and language. "However, in Alzheimer’s disease brains, many SOX9+ astrocytes stained negative for NFIA." (PMID 37533101, 2023).
aortic valve calcification (3 papers, 2011 to 2021). "In cultured aortic VICs, inhibition of the NOTCH signaling results in decreased expression of Sox9, and the loss of Sox9 function is associated with aortic valve calcification." (PMID 34239905, 2021). "Loss of Sox9 expression has been published to be associated with aortic valve calcification." (PMID 22110751, 2011). "Despite our data suggesting that reduced Sox9 function promotes matrix mineralization via relieved repression of Spp1, Osteopontin and Sox9 are both highly expressed in human valves excised from patients with end-stage calcific aortic valve disease." (PMID 22046352, 2011). "In contrast to Osteopontin, it is not so clear why Sox9 is overexpressed in late stages of calcific aortic valve disease." (PMID 22046352, 2011).
astrocytoma (3 papers, 2015 to 2021). "For GPR17, its expression was more confined to OLIG1+ cells in the oligodendroglioma, whereas a similar expression was found in the SOX9+ and OLIG1+ subpopulations in the explored astrocytoma." (PMID 33925547, 2021). "Here, we report that SOX9 and OLIG1 transcription factors, which specifically label astrocytes and oligodendrocytes in the normal brain, revealed the presence of two largely nonoverlapping tumoral populations in IDH1-mutant oligodendrogliomas and astrocytomas." (PMID 33925547, 2021). "Importantly, we observed that the tumor cells in the center zone displayed a prominent enrichment of stem cell markers Sox2 and Sox9, but did not express differentiated cell markers Olig2, CC1, S100β, and PDGFRα as observed in oligodendrocytoma and/or astrocytoma." (PMID 33863883, 2021).
Azoospermia (3 papers, 2013 to 2024). Absence of any measurable level of sperm,whereby spermatozoa cannot be observed even after centrifugation of the semen pellet. "We then used real-time RT-PCR to quantitatively analyze the expression levels of AR, SOX9 and AMH in the 23 and 33 patients with obstructive azoospermia with normal spermaotgensis and SCOS, respectively." (PMID 24098470, 2013). "Our results from immunohistochemistry of non-obstructive azoospermia revealed a low expression of sox9 and UTF1 in the locations that were not related to the Sertoli cells and undifferentiated spermatogonia respectively." (PMID 38486279, 2024). "Confocal scanning UV-laser microscope images proved the expression of UTF1 and sox9 out of the common compartment of seminiferous tubules of non-obstructive azoospermia." (PMID 38486279, 2024). "Studies have shown that the pattern of Sox9 expression in Sertoli cells differs significantly in patients with non-obstructive azoospermia or Sertoli cells only syndrome (SCOS)." (PMID 38486279, 2024).
cervical tumor (3 papers, 2015 to 2017). "In the present study, we found that SOX9 was down-regulated in the development and progression of human cervical tumor tissues." (PMID 26036262, 2015). "According to the available data in the Human Protein Atlas, most of tested cervical tumor samples were positive for protein expression of EGR3, NR4A2, SOX9, PA2G4, ENO1, and TEAD4." (PMID 28670312, 2017).
chondroblastic osteosarcoma (3 papers, 2019 to 2024). An osteosarcoma characterized by the presence of atypical cartilage of variable cellularity. "Chondroblastic osteosarcoma contains a unique cluster (Cos) expressing genes associated with hypertrophic chondrocyte differentiation; COL10, SOX9, and LOXL2." (PMID 38267611, 2024). "Notably, HIF1A serves as the hallmark gene for hypoxia, and previous studies have reported that HIF1A, a critical gene within the hypoxia pathway, activates SOX9 as a transcription factor in chondroblastic osteosarcoma." (PMID 39033089, 2024). "Besides, a recent study had shown that Fos could regulate the transcription of Sox9 and that the cfos-Sox9 axis is critical for the role of cfos in the induction of chondroblastic Osteosarcoma." (PMID 31379949, 2019).
chronic hepatitis C (3 papers, 2018 to 2023). "However, a recent study demonstrated that in human patients with chronic hepatitis C infection and in mouse models of liver injury (CCl4 injection and BDL), SOX9 is also found in regenerative hepatocytes and activated HSCs." (PMID 31615106, 2019).
colon adenocarcinoma (3 papers, 2020 to 2025). "Of 171 human colon adenocarcinomas studied, 70% of the tumors showed strong nuclear expression of SOX9 throughout the neoplastic epithelium." (PMID 40179020, 2025). "Presently, GEPIA data indicated that SOX9 was upregulated in 275 COAD (colon adenocarcinoma) samples relative to 349 normal tissues." (PMID 33318478, 2020).
colorectal adenocarcinoma (3 papers, 2016 to 2024). The most common type of colorectal carcinoma. "Of the top-ten cancer types, SOX9 had the leading high-risk variants for large intestine adenocarcinoma and stomach non-specified (NS) cancer." (PMID 36672963, 2023). "Inhibition of miR-30 using complementary locked nucleic acids (LNA30bcd) in both human IECs and human colorectal adenocarcinoma-derived Caco-2 cells resulted in significant up-regulation of SOX9 mRNA but, interestingly, significant down-regulation of SOX9 protein." (PMID 27261459, 2016).
colorectal tumor (3 papers, 2020 to 2023). "In such aberrant stem cells, Sox9 was shown as a cornerstone for altered cell plasticity, the maintenance of premalignant stemness, and subsequent colorectal tumor initiation." (PMID 37894295, 2023). "Additionally, we found a heterozygous nonsense mutation in APC and frameshift indels in known colorectal tumor suppressors; ATM, SOX9, RNF43, and ZFP36L2, of likely driver status." (PMID 32697969, 2020).
Cooks syndrome (3 papers, 2021 to 2022). "By modelling Cooks syndrome, a congenital limb malformation, genomic duplications upstream of SOX9/Sox9 creates a new TAD (neo-TAD) containing both the Kcnj2 gene and the Sox9 regulatory region leading to limb malformation due to ectopic Kcnj2 expression." (PMID 36114905, 2022).